AR (androgen receptor)
Diseases named in the same sentence as AR in open-access papers (continued):
Sharing a sentence is not in itself a finding about the gene and the disease.
breast carcinoma (continued). "A possible anti-proliferative effect of AR stimulation and pathway activation in breast cancer is suggested." (PMID 32218303, 2020). "Other studies too have found that breast cancers with discordant ER/AR expressions (ER+/AR- or ER−/AR+) demonstrated a worse prognosis in comparison to breast cancers with concordant expression (ER + AR+ or ER−/AR -) in multivariable models." (PMID 32928183, 2020). "AR is also investigated by many researchers as a potential therapeutic target in treatment of breast cancer." (PMID 32374753, 2020). "The AR is present in 70–80% of patients with breast cancer, and AR antagonists are under investigation in clinical trials." (PMID 32307594, 2020). "The proportion of tumors with positive AR expression in breast cancer patients varies widely, and mainly depends on the study population and the definition of AR positivity." (PMID 32290220, 2020). "Further study showed that 31% of CTCs were found to express AR mRNA, the levels of which vary depending on the breast cancer subtype." (PMID 31952272, 2020). "In this context, two PROTACs targeting the AR and estrogen receptor (ER) have reached the clinical setting being explored in two phase I studies in prostate and estrogen receptor-positive breast cancer." (PMID 32933565, 2020). "Some authors suggested assessment of Androgen receptor in breast cancer in the routine diagnosis, as part of a quadruple panel alongside the assessment of ER, PR, and HER2 to serve as an additional predictive and/or prognostic marker." (PMID 32374753, 2020). "The prognostic effect of AR in triple-negative breast cancer has been reported to be even more inconsistent than the effect in unselected breast cancers." (PMID 32290220, 2020). "High AR expression was a significant favorable prognostic factor for disease-free survival in the HRc(+)/HER2(−) breast cancer subgroup only (p = 0.026)." (PMID 32290220, 2020). "Four cases contained the IHC staining images of both proteins and visualization of the IHC staining images of these four cases suggested that TRPM4 and AR had similar expression profile in breast cancer cells." (PMID 32484822, 2020). "AR status was assessed using immunohistochemistry with tissue microarrays from 395 operable primary breast cancer patients who received curative surgery." (PMID 32290220, 2020). "These outcomes would be impactful not only for the advanced understanding of the role of AR, but also for new ways in which AR signaling can be inhibited to improve outcomes for women with AR+ breast cancer." (PMID 33062889, 2020). "A study reported that the AR potently inhibits the ERα activity which leads to the inhibition of breast cancer progression." (PMID 32290220, 2020). "A correct understanding of the prognostic value of AR in each breast cancer subtype would be of value in refining the prognostic and predictive outcomes in each specific subgroup of early breast cancer patients." (PMID 32928183, 2020). "At the same time, the expressions of MMP2 and MMP9 proteins in trinegative breast cancer cells treated with Bicalutamide were significantly decreased, and the expression of AR protein was also significantly decreased." (PMID 32332626, 2020). "An increasing number studies evaluated AR as a useful marker for the further refinement of breast cancer molecular subtype and as an emerging clinical target." (PMID 32374753, 2020). "Since AR expression has important consequences on the prognosis and treatment of breast cancer, further studies with an increased number of participants is necessary to confirm our reports." (PMID 32374753, 2020). "Efforts have been made to reveal the prognostic role of AR in breast cancer, but the results have been controversial to date." (PMID 32290220, 2020). "More specific research and exploration of the heterogeneity of AR signaling in the treatment of different types of breast cancers is needed." (PMID 32587770, 2020).
breast carcinoma (continued). "We recommend that validation at the protein level in larger series of breast cancer cases is required to resolve this, as well as to validate the association of TRPM4 with AR protein expression." (PMID 32484822, 2020). "The androgen receptor (AR) is an emerging prognostic marker and therapeutic target in breast cancer." (PMID 30795773, 2019). "Recently AR has been associated to cancer cell growth and survival in TNBC cell lines and chemo-resistance in breast cancer models in vitro and in vivo." (PMID 31540486, 2019). "Although a detailed discussion of the favorable effect of T in the breast is beyond the scope of this paper, it is known that T’s direct effect at the androgen receptor (AR) is antiproliferative, proapoptotic, and inhibits ER α and breast cancer growth." (PMID 31888528, 2019). "Considering the complexity of AR signaling and crosstalk in AR + breast cancer, AR antagonists have been investigated in combination with other targeted therapies." (PMID 31527644, 2019). "Recent preclinical data suggest that androgen receptor (AR) signaling plays a significant role in subsets of breast cancer." (PMID 31664946, 2019). "AR mRNA expression was analysed by RT-qPCR in breast cancer patients treated in the neoadjuvant TECHNO (n = 118, HER2-positive) and PREPARE trial (n = 321, HER2-positive and -negative)." (PMID 31728025, 2019). "Data from the TNBC subset of the prospective Nurses' Health Studies cohorts (n = 581) have reported, over a median follow up of 16.5 years, a significantly unfavorable breast cancer-specific survival in multivariable models for AR+ vs. AR- patients." (PMID 31245286, 2019). "They found in CTCs from bone-predominant breast cancer an AR signaling pathway constitutively activated due to a splicing variant named AR-v7." (PMID 31681412, 2019). "In our previous study, we have detected AR protein expression in all of the five breast cancer cell lines used here: MDA-MB453, MCF-7, MDA-MB468, MDA-MB231 and HCC1937; however, the highest AR protein expression was found in MDA-MB453 and MCF-7 cell lines." (PMID 31126320, 2019). "In contrast, AR signaling has been shown to antagonize cell proliferation in ER+ breast cancers in in vitro models." (PMID 30795773, 2019). "We leveraged the resources of the BIG 1–98 trial to evaluate AR protein expression as a marker of prognosis among postmenopausal women with early stage ER+ breast cancer." (PMID 30795773, 2019). "To further investigate the role of JQ1 in AR expressing breast cancer cells, we assessed protein-protein interactions among ATAD2, AR, as well as JQ1 targets including BRD2, and BRD4." (PMID 31527644, 2019). "AR/ER ratio has been reported to be an unfavorable prognostic marker in early primary breast cancer, but its role in the patients with advanced disease has to be cleared." (PMID 31110518, 2019). "We explored, within the EORTC10994 study, the outcomes for patients with molecular apocrine (MA) breast cancer, and defined immunohistochemistry (IHC) as androgen-receptor (AR) positive, oestrogen (ER) and progesterone (PR) negative." (PMID 30899086, 2019). "Recent studies increasingly support AR as a potential therapeutic target of AR-positive breast cancer." (PMID 31126320, 2019). "AR is expressed in 60–80% of breast cancers, with higher prevalence among estrogen receptor-positive (ER+) tumors." (PMID 30795773, 2019). "Eighty-two percent of breast cancers in this population were AR+ (≥ 1%) and the median AR expression was 12.5% (interquartile range [IQR] 2.1–30.6%)." (PMID 30795773, 2019). "Apparently the induction of the AR is an additional feature of these substances which are able to inhibit the proliferation of ER(+)/AR(+) breast cancer cells through activating AR as androgens." (PMID 31235695, 2019).
breast carcinoma (continued). "Different immunohistochemistry markers have been proposed for in situ characterization of molecular apocrine breast cancers, including androgen receptor (AR) and gross cystic disease fluid protein 15 (GCDFP15)." (PMID 31413819, 2019). "In our current study, we decided to combine AR, FOXA1 and the basal marker CK14 in order to better characterize the luminal-AR subgroup of feline mammary carcinomas." (PMID 31888566, 2019). "At the frequently used 10% threshold for AR positivity, from 58% to 90% of breast cancers are AR+, compared to 92% in cats with FMCs." (PMID 31888566, 2019). "The AR makes a contribution to the progression and development of breast cancer and is expressed in all stages." (PMID 31126320, 2019). "Our data show that AR expression is a prognostic marker in chemotherapy-treated breast cancer patients." (PMID 31728025, 2019). "Selective androgen receptor modulators (SARMs) have been proposed as therapeutics for women suffering from breast cancer, muscle wasting or urinary incontinence." (PMID 31319382, 2019). "Silencing or inhibiting USP14 triggers cell growth inhibition and cell cycle arrest by decreasing AR level in AR-positive breast cancer cells." (PMID 31126320, 2019). "In another study, AR overexpression led to tamoxifen resistance in in vitro models of breast cancer, implicating the involvement of AR signaling in tamoxifen resistance." (PMID 31664946, 2019). "There is growing evidence on the potential role of androgens and the AR in the pathogenesis of breast cancer." (PMID 31718606, 2019). "We have reported that USP14 mediates deubiquitination and stabilization of the AR in prostate and breast cancer cells." (PMID 31126320, 2019). "USP14 inhibition induced cell cycle arrest and apoptosis and overexpression of AR abrogated significantly the antiproliferative effect induced by USP14 siRNA in AR+ breast cancer cells." (PMID 31126320, 2019). "The high frequency of androgen receptor (AR) expression in primary breast tumours (70–90%) suggests that androgens are important modulators of breast cancer cell proliferation." (PMID 31684907, 2019). "The antiproliferative effect of the AR can be induced by the introduction of AR in AR(−) breast cancer cells." (PMID 31235695, 2019). "We tried to prove that the influence on the proliferation of breast cancer cells is due to activation of the AR and that the activated AR slows down the cell cycle by influencing the expression of the Cyclin D1 gene via histone modification." (PMID 31235695, 2019). "Preclinical and clinical data support differential effects of AR signaling in breast cancers, dependent on tumor ER expression." (PMID 30795773, 2019). "AR-signaling plays a crucial role in AR+ breast cancers as well, however, in such cases coordination of the cellular features and actions is quite complex and depends on the presence or absence of other signaling mechanisms." (PMID 31052484, 2019). "Androgen receptor (AR) has been extensively studied, but its role in relation to breast cancer patient prognosis remains to be clarified." (PMID 31110518, 2019). "Women with AR+ breast cancers were more likely to have smaller tumors (p < 0.001) and lower histologic grade tumors (p < 0.001)." (PMID 30795773, 2019). "ETS-1 also regulated resistance to other therapies, including androgen receptor inhibitor and paclitaxel in prostate and breast cancers, respectively." (PMID 31118072, 2019). "Luminal hormone receptor–positive breast cancers more commonly express AR (91%), TNBC expresses AR approximately 30% of the time." (PMID 31505803, 2019). "In this study, we demonstrated that drug targets for breast cancer including ER, PR, AR, and HER2 were successfully detected from the CTCs, highlighting the potential use of Hydro-Seq for precision medicine applications." (PMID 31092822, 2019).
breast carcinoma (continued). "Further, treatment of the murine WT276 breast cancer cell line, which expresses the androgen receptor (AR), with dihydroxy-testosterone (DHT) measurably increased the steady-state levels of the Aim2 mRNA and protein." (PMID 31771614, 2019). "Factor 12 also predicts insensitivity to TOP1-poisons and includes the canonical oncogenes such as ERBB2, TGFB3, ESR1 (AR), and FGFR4 that are strongly associated with breast cancer." (PMID 31695042, 2019). "The androgen receptor (AR) is discussed as a prognostic and/or predictive marker in breast cancer patients." (PMID 31728025, 2019). "In this review, we present a state of the art scenario about the role of AR in BC, highlighting the main issues about this “player” that is very debating especially for what concerns its function in different subsets of breast carcinomas." (PMID 30941159, 2019). "It has also been demonstrated that tamoxifen resistant breast cancers show elevated expression of AR and this resistance can be reversed by AR antagonists such as bicalutamide." (PMID 31749762, 2019). "AR has been identified as a potential therapeutic target in breast cancer, especially in the triple-negative breast cancer (TNBC) which shows the worst prognosis and metastases." (PMID 31126320, 2019). "Bicalutamide and enzalutamide are AR inhibitors that restore endocrine therapy sensitivity when used in anti-hormone therapy for breast cancer." (PMID 31413736, 2019). "A clinical study of enzalutamide in patients with metastatic/locally advanced triple negative, AR positive (AR staining > 0%) breast cancer has also reported promising results." (PMID 31769425, 2019). "The current study aims to explore the anticancer effect of a treatment combining AR antagonist enzalutamide with USP14 inhibition on breast cancer cells." (PMID 31126320, 2019). "It is also worth mentioning that the current understanding of AR in CAFs is mostly derived from hormone-dependent tumors, especially prostate and breast cancers." (PMID 30925918, 2019). "Approximately 90% of ER+ breast cancers express AR, while only 20–30% of ER− breast cancers are AR+." (PMID 30795773, 2019). "We evaluated the prognostic and predictive value of AR expression among 3021 postmenopausal ER+ breast cancer patients in the Breast International Group (BIG) trial 1–98." (PMID 30795773, 2019). "AR was also shown to maintain production of DNA damage response molecules in some breast cancer cells and it prevents the accumulation of damaged DNA in vitro." (PMID 31151151, 2019). "In contrast to our own study, several prior observational studies have found AR to be a predictive marker for endocrine therapy response in ER+ breast cancers." (PMID 30795773, 2019). "The anti-androgen agents (e.g., bicalutamide, enzalutamide) provided novel approach for development of therapeutic strategies in advanced breast cancer expressing AR." (PMID 30975222, 2019). "To date, androgen receptor (AR) has emerged as a promising new therapeutic target in breast cancer therapy." (PMID 31126320, 2019). "In summary, this study demonstrates a potential advantage of enzalutamide in combination of USP14 inhibition in AR-positive breast cancer treatment, compared with the treatment with each alone." (PMID 31126320, 2019). "A fourth protein marker, the androgen receptor (AR), is immunoexpressed in 60–80% of breast cancers, with similar proportions to prostate tumors, and specially expressed in HER2+ and triple-negative breast tumors." (PMID 31737566, 2019). "Previous studies have associated the trinucleotide repeat polymorphism (CAGn) in the exon 1 of the androgen receptor gene (AR) and mutations in BRCA1 and BRCA2 with breast cancer among Filipino women." (PMID 31030479, 2019). "The androgen receptor has been seen to be expressed in a large percentage of breast tumors including hereditary forms of breast cancer." (PMID 31749762, 2019).
breast carcinoma (continued). "Some argue that the prognosis of breast cancer with high AR is better because these cancers are well differentiated." (PMID 31151151, 2019). "In vitro models of AR+/ER− breast cancers have indicated that AR signaling can drive cell proliferation in these cancers." (PMID 30795773, 2019). "In conclusion, we provide evidence that there seems to be an interaction between AR expression and chemotherapy-responsiveness in breast cancer patients." (PMID 31728025, 2019). "Here we demonstrated, in estrogen receptor α (ERα)-positive breast cancer cells, an androgen-dependent mechanism through which ligand-activated androgen receptor (AR) decreases estradiol-induced cyclin D1 protein, mRNA and gene promoter activity." (PMID 31684907, 2019). "Our results provide strong experimental basis for this combination to become a rational and new therapeutic strategy for AR positive breast cancer." (PMID 31126320, 2019). "The resurgence of interest into the function of AR in breast cancer has resulted in various emergent clinical trials evaluating anti-AR therapy and selective androgen receptor modulators in the treatment of advanced breast cancer." (PMID 30416486, 2018). "We previously found AR activation induced a robust increase of let-7 family members in breast cancer cell lines, including let-7a." (PMID 29423076, 2018). "To assess the subtype distribution of AR amongst the three major breast cancer subtypes, we stratified The Cancer Genome Atlas into putative HER2-positive, Luminal A/B and Triple Negative subtype using the available RNA-seq data." (PMID 30279965, 2018). "In breast cancer tissues, AR and let-7a expression were correlated with the phenotype of CD44+/CD24-/low." (PMID 29423076, 2018). "It is notable that PIP is a key target of AR that is required for cell cycle progression and acts an effector of AR function in breast cancer." (PMID 29577611, 2018). "Studies show androgen-receptor (AR) remains present in 80–90% of metastatic breast cancers providing support for blockade of AR-signalling." (PMID 29991699, 2018). "In breast cancer tissue, we identified that AR expression was positively correlated with let-7a expression, but negatively with CD44+/CD24-/low phenotype of cancer cells." (PMID 29423076, 2018). "Though the androgen receptor (AR) is present in normal as well as malignant breast tissue, its expression level varies according to the breast cancer subtype." (PMID 30558195, 2018). "A positive correlation was detected between the expression levels of AR and KCa1.1 transcripts in human primary breast cancer tissues." (PMID 29713287, 2018). "In contrast, some studies showed that AR promotes the growth of ER+ breast cancer and TNBC via distinct mechanisms." (PMID 30547831, 2018). "The AR and ERα are critical drivers of prostate and breast cancer, respectively; therefore, AR and ERα were assessed as examples of major oncogenic signaling pathways in the PDE model." (PMID 30117261, 2018). "AR activation in breast cancer cells facilitates downstream gene expression that drives tumorigenesis in a similar manner to ER." (PMID 30577860, 2018). "As alluded to above, understanding the unique locations of the AR and the functional significance of this is imperative to better understanding of its complex role in breast cancer." (PMID 30416486, 2018). "The number of vital CETCs was determined from blood of 66 patients suffering from breast cancer and the expression of AR and ER on these cells was investigated using the maintrac method." (PMID 30547831, 2018). "Work from our lab has found that in AI resistant breast cancer, 4-dione enhances AR recruitment to the promoter of ER target genes." (PMID 30416486, 2018). "Our lab has previously identified that AR expression is acquired in a murine model of HER2-positive breast cancer following Periostin deletion." (PMID 30279965, 2018).